ID1 (inhibitor of DNA binding 1)
Diseases named in the same sentence as ID1 in open-access papers (continued):
Sharing a sentence is not in itself a finding about the gene and the disease.
tumor (continued). "Besides, given the outcome that ID1 was related to tumor metastasis and the fact that immune system, especially tumor-infiltrating immune cells, contributes to tumor metastasis cascade, we inferred that ID1 might also affect tumor metastasis through immune system." (PMID 33178820, 2020). "Conversely, depletion of Id1 and Id3 in the 4T1 murine model of TNBC demonstrates that Id1/3 are required for cell proliferation and self-renewal in vitro, as well as primary tumor growth and metastatic colonization of the lung in vivo." (PMID 32766238, 2020). "Therefore, Id1 targeting may contribute to significantly increasing the efficacy of anti-PD-1 ICIs and may help to overcome treatment resistance by significantly enhancing tumor infiltration by immune cells." (PMID 33126649, 2020). "Based on these results, we decided to further investigate the potential relationship between Id1 and the recruitment of CD8+ T cells into the tumor." (PMID 33126649, 2020). "In analysis of 532 NSCLC patients' samples, Id1 was found significantly correlated with EMT-related proteins and it enables the tumor and the microenvironment to colonize the liver." (PMID 32410828, 2020). "To validate this result, we analyzed the expression of ID1, LC3B, and ATF6 in xenograft tumor tissues derived from previously conducted animal experiments." (PMID 32080166, 2020). "We observed that a selective depletion of CD8+ T cells completely abrogated the antitumor efficacy of the Id1-PD-1 double blockade against LLC cells and restored the expected tumor growth (Id1sh/DPBS, n.s.; Id1sh/anti-PD-1, p = 0.0425)." (PMID 33126649, 2020). "In colon cancer, knockdown of ID1 and ID3 have been shown to impair self-renewal of colon cancer tumor initiating cells, reduce tumor growth and enhance sensitivity to chemotherapy." (PMID 31602000, 2019). "The active tivantinib as a single agent showed strong inhibition of various tumor-promoting signaling molecules, such as reduced RalB, CD44, c-Myc, and Id1 as well as inhibition of Akt activation, whereas the inactive enantiomer did not elicit much effect." (PMID 31100813, 2019). "Increased Id-1 expression was likewise demonstrated in HCC and oxaliplatin-resistant HCC, and was significantly correlated with tumor malignancy and poor prognosis." (PMID 31250351, 2019). "Undoubtedly, our retrospective analysis of microarray ID1-expression indicated that ID1 is already expressed in normal intestinal stem cells in accordance with a previous study, and therefore, the ID1-expressing population might play a role in tumor initiation besides propagation." (PMID 31013771, 2019). "ID1 inhibits DNA binding and the transcriptional activity of HLH proteins which leads to tumour growth and angiogenesis." (PMID 28582447, 2017). "The gene profiles indicated that YM155 down-regulated ID1 and BIRC5 which are tumour promoters, and upregulated CYLD and FOXO1 which are tumour suppressors." (PMID 28582447, 2017). "To investigate the role of Id1-induced IGF2 on VEGF-mediated tumour angiogenesis, we first compared the microvessel density in subcutaneous tumour xenografts established from KYSE150-Id1-shCON, KYSE150-Id1-shIGF2 and KYSE150-CON-shCON ESCC cells." (PMID 28186102, 2017). "Accordingly, inhibition of Id1 and p65 with shRNA leads to down-regulation of MMP9 and reduction of tumor cell migration." (PMID 28122577, 2017). "When expression of tumour suppressor ΔNp63α was induced in MCF-7 cells, the BMP target gene ID-1 was upregulated and proliferation significantly reduced." (PMID 28733469, 2017). "ID1 is an inhibitor of DNA binding that interacts and inhibits the transcriptional activation ability of basic HLH proteins which leads to tumour growth and angiogenesis." (PMID 28582447, 2017). "Our results indicate that the elevated phosphorylation level of IκBα was accompanied with high Id-1 expression in NSCLC tissues, when compared with corresponding non-tumor tissues." (PMID 29233161, 2017).
tumor (continued). "R193A/K195A mutations also impaired EGFR-stimulated cell proliferation, cell migration, colony formation, tumor growth, GSC self-renewal, p-STAT3 and ID1 expression." (PMID 29129908, 2017). "In summary, we described a molecular mechanism whereby ID1 regulated Wnt/ β-catenin/c-MYC pathway, which in turn activated the PPP, thus encouraging tumor proliferation and oxaliplatin chemoresistance in HCC." (PMID 29169374, 2017). "Established xenografts from H1299 cells stably expressing an Id1 promoter regulating luciferase were treated with DMH2 or LDN and tumor luminescence was measured before and after treatment." (PMID 27048361, 2016). "We demonstrate that upregulation of Id1, primarily in response to tumour-derived TGFβ, redirects BMDC differentiation towards Id1-high expressing MDSCs with a reciprocal decrease in DC numbers." (PMID 25924227, 2015). "Id1 overexpression results in a systemic immunosuppressive phenotype that inhibits CD8 T-cell proliferation and increases primary tumour growth and metastatic progression." (PMID 25924227, 2015). "ID1 and ID3 are essential for angiogenesis and neurogenesis during development and tumor growth, with ID1+/− ID3−/− knockout mice unable to support the growth of tumors." (PMID 25207642, 2014). "Since TGF-β can derive from both tumor and host tissue stroma, this implies a regulation of the TGF-β-ID1-induced MET plasticity by environmental conditions and contextual signals and a possible role of ID1 in determining organ tropism." (PMID 25927844, 2014). "On the other hand, we found FAS, FPR1, ID1, IL10, PCGF2, VDR among downregulated proteins: all are involved in tumor immune-escape through induction of apoptosis and anti-inflammatory activities." (PMID 25594007, 2014). "Therefore, Id1 may be one of the targets regulated by EGCG for tumor inhibition." (PMID 23900621, 2013). "Recently, more reports have shown that miR-29 family regulated tumorigenesis and tumor progression by targeting DNMT3A, DNMT3B, TIAM1, cyclin E, MMP2, ID1, SPARC and COL3A1." (PMID 23936390, 2013). "In this dataset, positive TCF3, ID1 and ID4 expression were more frequent (Chi-square test, p = 0.033, p<0.001, and p<0.001, respectively) in the basal-like tumours." (PMID 23555842, 2013). "In the present work we demonstrate that MAGE I expression can regulate ZNF382, an important KZNF tumor suppressor, and can affect the ability of ZNF382 and KAP1 to bind and regulate a downstream target, the ID1 oncogene." (PMID 21876767, 2011). "Here, an examination of NPC primary tumours revealed a positive correlation between LMP1 and Id1 expression in NPC cells." (PMID 20565867, 2010). "In this study, we also correlated Id-1 and TNF-β with the Gleason score of the tumours and Gleason grade of individual cores." (PMID 20010941, 2010). "For example, tumour T1 shows strong staining for both LMP1 and Id1, but weak Foxo3a nuclear staining." (PMID 20565867, 2010). "We demonstrated that intracellular-delivered Id1/3-PA7 colocalised to Id1 and Id3 and promoted increased expression of the tumour suppressor CDKN2A in a dose-dependent manner." (PMID 20842131, 2010). "In contrast, tumour T3 showed strong nuclear staining of Foxo3a but weak detection of LMP1 and Id1 proteins." (PMID 20565867, 2010). "BYJHD can down-regulate the phosphorylation of Smad protein by inhibiting the expression of tumour ACVRL1, and reduce the expression of the target gene ID-1 and the surface marker CD34 in the tumour microenvironment to regulate tumour angiogenesis, leading to anti-NSCLC effects." (PMID 41579221, 2026). "Given our findings, TRIM21-based PROTACs may be developed specifically degrade ID1 in PAAD, especially in hypoxic tumor areas where malignancy is driven by ID1 stability." (PMID 40919143, 2025). "Finally, in vivo xenograft experiments were conducted to evaluate the impact of ID1 and TRIM21 on tumor growth." (PMID 40919143, 2025).
tumor (continued). "Considering the alterations in PRMT2 that influence the transcription of ID1, ID2, and ID3, we demonstrated that PRMT2 may also regulate the tumour stemness of OSCC." (PMID 40078091, 2025). "The same knockdown did not cause alterations in Neu-induced tumors; mammosphere formation, which is a measure of tumor-initiating capacity, is lower in Neu tumors but is not decreased by the knockdown of Id1 and Id3." (PMID 41303422, 2025). "CDH5, ID1, H2BC10, and ITLN1 were common DEGs in the tumor and stroma areas." (PMID 40422184, 2025). "While ID1 is not a classical oncogene, it promotes tumor progression by sustaining a progenitor-like state characterized by enhanced proliferative capacity, resistance to apoptosis and maintenance of stemness properties." (PMID 40919143, 2025). "Id1 and Id3 expression, which reflect an immature stage, is observed in the tumor cells of Wnt-1-driven tumors but not in Neu-induced tumor cells." (PMID 41303422, 2025). "To determine whether the tumor suppressive effects of TRIM21 are dependent on ID1, we performed ID1 knockdown in both control and TRIM21‐deleted KYSE30 cells." (PMID 40652518, 2025). "Notably, some genes (e.g., MET, HSPA6, ID1, MECOM, POU2AF1, SFRP4, CDH1) exhibited expression predominantly in tumor cells and a limited number of other cell types." (PMID 40954493, 2025). "Consistently with the effects of trametinib on Id1 expression in vitro, IHC analysis revealed a downregulation of Id1 expression in CMT-167 and LLC tumor tissues in vivo (CMT167: Control: 1.12 ± 0.3038, CMT-167 TRAM: 0.04059 ± 0.0097; LLC: Control: 5.96 ± 1.617, TRAM: 2,339 ± 1.946)." (PMID 38643157, 2024). "report that Id1 overexpression leads to systemic immunosuppression by negatively regulating key molecules involved in dendritic cell differentiation and suppressing CD8+ T cell proliferation, thereby promoting primary tumour growth and metastatic progression." (PMID 39676870, 2024). "First, RT-qPCR was used to assess ID1 and ID3 expression in BM tumour cells." (PMID 39676870, 2024). "It is crucial to highlight that both ID1 and ID3 play central roles in cancer biology, acting as transcriptional regulators that exert their influence on the intracellular transcriptional machinery of tumour cells." (PMID 39676870, 2024). "Another study demonstrated that Id1 increased the expression and secretion of IGF2 in a variety of human cancer types and that targeting IGF2 inhibited growth and metastasis in mice and enhanced tumor chemosensitivity." (PMID 36672737, 2023). "The inhibitory effect of Id1 knockout in TAMs on CSC marker expression, tumor sphere formation ability, and tumor invasiveness could be reversed by depletion of Serpinb2 (Serpinb2KD)." (PMID 37996458, 2023). "We also verified the positive correlation between ID1 expression and SOX9 (p = 6.90e‐05, r = 0.20), EPCAM (p = 5.37e‐06, r = 0.23), CD24 (p = 1.82e‐07, r = 0.27), and CLDN4 (p = 6.04e‐05, r = 0.18) expression in HCC tumor tissue from TCGA datasets." (PMID 37085918, 2023). "In addition, depletion of Id1 in TAMs increased the expression of interferon-γ (IFN-γ) and Granzyme B in tumor-infiltrating CD8+ T cells." (PMID 37996458, 2023). "Consistently in both mouse and human, ID1 showed a dramatically increased transcription with the progression of PDAC, which was further confirmed by multiple microarray datasets on PDAC and matched non-tumor tissues." (PMID 35941362, 2022). "Inhibition of Olig2 but not deletion of Id1 within Id1-low cells significantly prolongs the survival of tumor-bearing mice, underscoring the importance of non-self-renewing lineages in disease progression." (PMID 34302526, 2022). "Id-1 and Id-3 expression is seen in tumor cells of Wnt-1 driven tumors but not in Neu-induced tumors." (PMID 34736527, 2021).
tumor (continued). "Here, we demonstrate the potential role of BMP9 and its target transcription factor inhibitor of DNA‐binding protein 1 (ID1) in the activation of EpCAM+ CSC properties in HCC, and we demonstrate the effect of BMP receptor inhibitors, which suppress HCC tumor growth by inhibiting BMP9‐ID1 signaling." (PMID 33834612, 2021). "In addition, the administration of TMP inhibited the tumor growth of A549 xenografts in nude mice, with reduced expression of CD31, phosphorylated Smad1/5/8, and Id-1." (PMID 34975475, 2021). "Furthermore, BMP receptor inhibitors successfully suppressed BMP9‐induced ID1 expression and CSC phenotypes in HCC in vitro and tumor growth of HCC xenografts in vivo." (PMID 33834612, 2021). "A previous study has shown ID1 to inhibit TWIST-mediated EMT to promote mesenchymal–epithelial transition at metastatic sites where SNAI1 expression is low and underscores that ID1 does not affect SNAI1-mediated EMT at the primary tumor site." (PMID 34869246, 2021). "Tumor promotion resulting from NR4A1 knockout was abolished when ID1 was knocked out simultaneously, whereas the tumor inhibitory effect of ID1 knockout was not significantly affected by NR4A1 knockout." (PMID 33990575, 2021). "In terms of metabolisms, the ID1/HIF1-interaction explains why tumor cells use different energy substrates in non-hypoxic and hypoxic conditions." (PMID 34820369, 2021). "Taken together, these experiments suggest that the lack of Id1 expression in both tumor cells and the tumor microenvironment, along with the blockade of PD-1/PD-L1 axis, exerts the most potent antitumor effect in murine KRAS-driven LUAD." (PMID 33126649, 2020). "Taken together, these data suggest that ID1 and ID3 may play roles in multiple stages of tumor growth and metastasis by regulating different processes in attached versus detached cancer cells." (PMID 32661241, 2020). "After that, other indicators such as Tumor-Node-Metastasis classification (TNM), lymph nodes, serum calcium, and hemoglobin were studied to evaluate the clinical manifestations between lowly expressed ID1 group and highly expressed ID1 group." (PMID 33178820, 2020). "Next, we studied the impact of the combined blockade when both the host and the tumor cells lacked Id1 expression." (PMID 33126649, 2020). "Id1 can increase MMP gene expression, leading to tumor cell invasion." (PMID 32410828, 2020). "Moreover, ID1 and ID3 are required for angiogenesis and vascularization of tumor xenografts, necessary for macro-metastasis development." (PMID 30899759, 2019). "Similarly, PDAC patients show overexpression of inhibitor of differentiation, Id1, a helix-loop-helix (HLH) protein, which correlated with tumor angiogenesis and a low survival rate." (PMID 31100813, 2019). "Id1/Id3 double knockout results in the lack of the tumor-initiating potential and increases the sensitivity of CSCs to the chemotherapeutic agent oxaliplatin." (PMID 28122577, 2017). "Additionally, overexpression of Id1 activates EGFR and NF-κB, resulting in aggressive tumor progression." (PMID 28122577, 2017). "In the present study, we examined whether Id1-induced IGF2 plays any role in tumour angiogenesis and whether it exerts paracrine effects in the tumour microenvironment and tumour macroenvironment to further facilitate cancer progression." (PMID 28186102, 2017). "Our study demonstrated a novel paradigm of ESCC progression that involves the orchestration of cancer and non-cancer cells in the tumour micro- and macroenvironments by the Id1/IGF2/VEGF/VEGFR1 cascade." (PMID 28186102, 2017).
tumor (continued). "Moreover, the association of TRIM24 with H3K23ac is important for EGFR-stimulated cell proliferation, cell migration, colony formation, tumor growth, GSC self-renewal, p-STAT3, ID1 expression and the binding of TRIM24, H3K23ac and STAT3 with ID1 promoter." (PMID 29129908, 2017). "In addition, the final mean tumor weight in 97H–OXA-Ctrol group was significantly higher than that in 97H–OXA-shID1 group (P = 0.002), indicating that ID1 knockdown inhibited tumor proliferation of 97H–OXA cells in vivo." (PMID 29169374, 2017). "The expression of Id-1 was significantly upregulated in tumor tissues compared with the adjacent noncancerous tissues in these 96 NSCLC patients." (PMID 29233161, 2017). "Id1 overexpression leads to systemic immunosuppression by downregulation of key molecules involved in DC differentiation and suppression of CD8 T-cell proliferation, thus promoting primary tumour growth and metastatic progression." (PMID 25924227, 2015). "Considering these data, one may assume that perturbation in Id1 expression/function may entail other aberration in activity of CXCL1, COX2, EREG and MMP1 resulting in the metastatic proclivity of a tumour." (PMID 25598217, 2015). "In other mouse and human tumor cell lines Id2 was not dominant whereas Id1 and/or Id3 were (unpublished data)." (PMID 26079374, 2015). "When examining the functional outcomes of systemic Id1-induced tumour immunosuppression, we identified both antigen non-specific and specific mechanisms by which Id1-expressing MDSCs exert their immunosuppressive effects." (PMID 25924227, 2015). "To assess whether Id1 is a direct regulator of MDSC and DC differentiation during tumour progression, we performed a series of experiments using Id1−/− mice." (PMID 25924227, 2015). "The role of ID1 in angiogenesis is further backed up with evidence that tumours failed to grow and/or metastasise in ID1 +/−; ID3 −/− mice due to poor vascularisation." (PMID 26577912, 2015). "Genetic inactivation of Id1 largely corrects the myeloid imbalance, whereas Id1 overexpression in the absence of tumour-derived factors re-creates it." (PMID 25924227, 2015). "Taken together, these results suggest that GCIP is a potential tumor suppressor in NSCLC and that suppression of Id1-mediated oncogenic properties may be a key mechanism by which GCIP can potently suppress NSCLC tumor progression." (PMID 24970809, 2014). "Interestingly, we identified expression of Id1, an inhibitor of DNA binding gene, and a regulator of differentiation, specifically in PDIC tumor cells by histological analysis." (PMID 23691228, 2013). "A previous study demonstrated that ID1 promotes tumor progression, although there is no direct evidence that ID1 is involved in GBM cell proliferation." (PMID 24137437, 2013). "PFS also showed differences in favor of patients showing no Id1/Id3 tumor co-expression although a statistical significance was not achieved (30 months vs 1 month, p = 0.219)." (PMID 23311395, 2013). "It is also worth noting that expression levels of different Notch target genes are not uniform in each Id1 tumor or among all samples." (PMID 22393458, 2012). "No statistical significance was found when examining all (data not shown) or ER-negative patients however, high ID1 expression was associated with the shortest RFS in CCND1low ER-positive tumours." (PMID 21955753, 2011). "Mice lacking Id1 and Id3 genes (Id1+/−Id3−/−) are resistant to xenotransplanted tumour grafts and show defects in tumour neoangiogenesis." (PMID 20842131, 2010). "Genetic studies on Id1 and Id3 knock-out mice have shown that Ids are expressed in endothelial progenitor cells (EPC) and are required for EPC mobilization from the bone marrow during pathological tumor-induced neoangiogenesis." (PMID 21293053, 2010).